HIF1A (hypoxia inducible factor 1 subunit alpha)
Diseases named in the same sentence as HIF1A in open-access papers (continued):
Sharing a sentence is not in itself a finding about the gene and the disease.
cancer (continued). "Our previous study showed that osteopontin was able to induce HIF-1α expression and promote HO-8910 cancer cell survival through Akt activation." (PMID 23946798, 2013). "These in vitro data suggest the possibility that hypoxia-induced HIF-1α plays an important role in the systemic spread of cancer cells via accelerating intravasation into vessels." (PMID 24216696, 2013). "Due to the important roles of Annexin A3 and HIF-1α in cancer progression, the correlation between Annexin A3 and HIF-1α expression was analyzed." (PMID 24260057, 2013). "Hypoxia-inducible factor-1α (HIF-1α) has been found to correlate with the increased expression of vascular endothelial growth factor (VEGF) in various cancer types." (PMID 24260057, 2013). "A screen of drugs in clinical trials and/or use revealed that digoxin and other cardiac glycosides inhibit HIF1α protein synthesis and expression of HIF1α target genes in cancer cells." (PMID 24216979, 2013). "Hypoxic conditions that induced nuclear accumulation of HIF-1α upregulated hTERT gene promoter activity in human cancer cells." (PMID 22720091, 2012). "On the basis of their importance for cancer cell survival, HIF-1α and VEGF are preferred targets for anti-cancer strategies." (PMID 23166763, 2012). "Consistent with HIF-1α induction by exposure to cobalt chloride (CoCl2), HIF-1α expression was strongly induced in human cancer cells (HT29, DLD-1, H1299) maintained in the hypoxia chamber." (PMID 22720091, 2012). "Increased HIF-1α levels are frequently found in many human cancers and are stimulated by low oxygen but also by genetic alterations." (PMID 23144866, 2012). "Among the 12 hypoxia-inducible genes in irradiated BALB/c, both HIF1α and STC2, a HIF1A target gene, were overexpressed in human cancers and pre-neoplastic breast lesions." (PMID 23077491, 2012). "In this regard, hypoxia-inducible factor 1α (HIF1α) has been identified as a key regulator of the hypoxic response, activating various cancer-related genes such as VEGF, CAIX, and GLUT1." (PMID 22970168, 2012). "Immunohistochemical analysis revealed that ER-400583-00 suppressed the proliferation of cancer cells most prominently in areas distal to the region of blood perfusion, where HIF-1α-expressing hypoxic cancer cells were located." (PMID 22211243, 2012). "Various receptors, receptor-activated kinases, small GTPases, and transporters are regulated by hypoxia/HIF-1α to play a significant role in cancer metastasis." (PMID 23241400, 2012). "We investigated the association of cumulative exposure to these carcinogens with NOTCH1, HIF1A and other cancer-specific proteins in lung tissue from uranium miners." (PMID 23028920, 2012). "HIF-1α is expressed in many human cancers and is considered a therapeutic target for treating malignant diseases of diverse aetiologies." (PMID 22178269, 2012). "Recently, a remarkable progress has been made to seek selective HIF-1α inhibitors for cancer treatment from herbal medicine." (PMID 22844340, 2012). "HIF-1α leads to the upregulation of genes involved in certain aspects of cancer progression, including angiogenesis and metastasis." (PMID 22616919, 2012). "HIF1α activity is regulated by several pathways, including the mitogen-activated protein kinase cascade, and p38α has been demonstrated to be involved in the stabilization of HIF1α in various normal and cancer cell types." (PMID 22481926, 2012). "Hypoxia is a basic feature of cancer where HIF1A has been identified as a key regulator of energy metabolism and other oncogenic pathways." (PMID 23028920, 2012). "Actually, HIF1α has been reported to be activated by artemisinin in several cancer cell lines including HepG2 and MCF7 cells." (PMID 22900042, 2012).
cancer (continued). "Although CT was known to have antiproliferative, apoptotic, and antiangiogenic activities in cancers in normoxia, the antitumor activity of CT in hypoxic PC-3 cells was associated with PI3K, HIF-1α and AEG-1, signaling pathways in the current study." (PMID 23243443, 2012). "PK dependence of glycolytic enzyme expression is an interesting parallel to the humans in respect to cancer development: hydroxylated PKM2 leads to an upregulation of glycolytic enzymes through interacting with hypoxia inducible factor -1α (HIF1α)." (PMID 23154538, 2012). "Although the PyMT model is classified as a luminal-like cancer, late-stage tumors such as the ones utilized to generate HIF-1α WT and KO cells are ER-." (PMID 22225988, 2012). "HIF-1α, being the best characterized inducer of gene transcription in hypoxic cells, is overexpressed in various cancer types including EWS, and a key role for this protein in hypoxic induction of CXCR4 has been described." (PMID 23249693, 2012). "Interruption of HIF-1α signaling revealed to inhibit cancer growth in both in vitro and in vivo experimental models." (PMID 22844340, 2012). "AKT2 and HIF-1α activate transcription of a plethora of genes involved in cancer cells proliferation, survival, and progression." (PMID 22511931, 2012). "HIF-1α is overexpressed in many human cancers including NPC, and several lines of evidence indicated its essential role in tumorigenesis." (PMID 22952803, 2012). "Our findings revealed that ER-400583-00 suppressed the proliferation of cancer cells most prominently in areas distal to the region of blood perfusion, where HIF-1α-expressing hypoxic cancer cells were located." (PMID 22211243, 2012). "The metabolite of oltipraz, a cancer chemopreventive drug, inhibited HIF-1α due to increased expression of pre-miR-199a-5p in colon cancer cells." (PMID 22942713, 2012). "The regulatory outcome is more complex since in cancer cells, HIF-1α can bind the TWIST1 promoter directly and control its expression." (PMID 22942713, 2012). "In view of this, the benefits of HIF-1α inhibition in cancer therapy seem questionable as it can undo cell cycle arrest under hypoxic conditions and prevent cell death." (PMID 23028659, 2012). "Taken together our data allow us to conclude that TNFα uses a distinct and complex signaling mechanism to induce accumulation of HIF-1α in cancer cells." (PMID 22355351, 2012). "In order to understand the meaning of HIF redox regulation in cancer resistance, we analysed the effect of different antioxidants in HIF-1α accumulation.." (PMID 23144690, 2012). "The results showed that cancer cells with higher HIF-1α expression were located distal to the region of blood perfusion." (PMID 22211243, 2012). "Epidermal growth factor, transforming growth factor-β, fibroblast growth factor and hypoxia-inducible factor 1α (HIF1α) released in the microenvironment of the primary cancer are the biological agents that have the capacity to induce EMT in cancer cells." (PMID 22676510, 2012). "A number of anti-cancer agents have been reported to decrease HIF-1α activity in cells in culture however, only a few of the reported HIF-1α inhibitors demonstrated antitumor activity in vivo." (PMID 21819554, 2011). "Novel strategies to target HIF-1α in tumors are being developed to counter hypoxia's pro-survival effect on cancer cells." (PMID 21853076, 2011). "HIF-1α and c-Myc are two major oncogenic transcription factors known to regulate metabolism in cancer cells." (PMID 22093145, 2011). "Since HIF-1α is a master transcriptional regulator of glucose metabolism in cancer cells, we investigated the role of HIF-1α in glycolysis in imatinib-resistant cells." (PMID 21789194, 2011).
cancer (continued). "In cancer cells, for example, insulin and certain growth factors are known to increase HIF-1α protein synthesis in a 59 untranslated region-dependent manner via the activation of the phosphatidylinositol 3-kinase/Akt pathway and mTOR signaling." (PMID 22102864, 2011). "Glycolysis is another thread that connects MDR and hypoxia; increased glycolysis is characteristic of MDR cancer and most glycolytic enzymes are HIF-1α targets that are transcriptionally activated in response to hypoxia." (PMID 21320311, 2011). "Cancer-specific aerobic glycolytic metabolites have been shown to promote HIF1α activation under normoxia conditions by interacting with the HIF prolyl hydroxylases (PHD 1–3)." (PMID 21283817, 2011). "The link between HIF-1α and apoptosis, a major determinant of cancer progression and treatment outcome, is poorly understood." (PMID 21248371, 2011). "According to the authors, HIF-1α alone can mediate the majority of hypoxic effects in gliobastoma neurospheres, indicating a pivotal role of HIF-1α in clonal expansion of cancer stem cells." (PMID 21824412, 2011). "Accumulation of succinate and fumarate in cancer cells induces inhibition of HIF prolyl hydroxylases allowing the nuclear translocation of HIF-1α." (PMID 21789194, 2011). "The HIF-1a subunit is stabilized by low oxygen, genetic alteration and cobaltous ions, and its over-expression correlates with drug resistance and increased cancer mortality in various cancer types, therefore representing an important anticancer target." (PMID 22202117, 2011). "HIF-1α can up regulate the enzymes of the glycolytic pathway and lactic acid dehydrogenase, sustaining the Warburg effect in cancer cells." (PMID 22093145, 2011). "In clinical studies, it has been repeatedly confirmed that HIF-1α expression correlates with a poor prognosis for various cancer patients after radiation therapy." (PMID 24212970, 2011). "HIF-1α has also been found in cancer stem cells and hence it is an effective way of targeting the drug or monoclonal antibody via the use of nanoparticle." (PMID 22082307, 2011). "Increased VEGF production and cell motility are typical events occurring in hypoxic cancer cells, due to the accumulation of hypoxia-inducible factor-1α (HIF-1α), which plays a major role in the transcriptional activation of genes encoding angiogenic factors." (PMID 22216344, 2011). "The switch (called Haps59) consisted of a fusion between a yeast cytosine deaminase (an enzyme that can activate a prodrug) and the CH1 domain of the human p300 protein, a domain that can bind to the cancer marker HIF-1α." (PMID 22096548, 2011). "HIF-1α synthesis and transactivation can also be activated by non-hypoxia-mediated mechanisms such as genetic alterations in a variety of cancer types." (PMID 21248371, 2011). "Under both normoxia and hypoxia, HIF-1α mRNA is expressed constitutively in many cell types, including cancer cells and endothelial cells." (PMID 20953377, 2010). "This synergistic effect was substantially decreased in cancer cells transfected with HIF-1α-ΔODD, indicating that downregulation of HIF-1α was the mechanism of this synergistic effect." (PMID 21209911, 2010). "Cancer cells with disruption of both HIF-1α and HIF-2α or oncogenic KRAS showed decreased aerobic respiration and ATP production, with increased ROS generation." (PMID 21073737, 2010). "Rapamycin is a specific inhibitor of mTOR and inhibits both the stabilization and the transcriptional activity of HIF-1α in hypoxic cancer cells." (PMID 20169098, 2010). "This constitutes the first report of elevated chemotherapy-induced senescence via functional inactivation of HIF-1α in an established human cancer cell line." (PMID 20706634, 2010). "We used a real-time quantitative reverse transcription PCR assay to measure mRNA expression levels of 4 alternatively spliced transcripts of HIF-1α in breast specimens of 53 primary cancers and 29 normal tissues or benign lesions." (PMID 20624301, 2010).
cancer (continued). "Inhibition of tumoral hypoxia inducible factor (HIF-1α) is thus becoming an increasingly attractive therapeutic target in the treatment of cancer." (PMID 20398289, 2010). "Overexpression of HIF-1α in human cancers is usually correlated with poor prognosis and poor therapeutic response." (PMID 20932347, 2010). "Hypoxic regulation of EMT has been shown to be involved in cancer progression and metastasis, and HIF-1α has been identified as a regulator of EMT in several cancer cell lines." (PMID 24281221, 2010). "In contrast, overexpression of HIF-1α in cancer cells that were originally sensitive to the treatment conferred substantial resistance to anti-EGFR therapy." (PMID 21209911, 2010). "The results shown in our current study clearly demonstrate a strong induction of apoptosis in cancer cells by combination treatment using cetuximab and 1, 9 PA that acted through targeting HIF-1α." (PMID 21209911, 2010). "Next, we assessed the role that HIF-1α plays in maintaining the characteristics of cancer stem cells (CSCs)." (PMID 20515450, 2010). "Neo-angiogenesis occurs in an uncoordinated fashion in malignant tumors, leading to hypoxia, inactivation of prolyl hydroxylases and inhibition of HIF1α degradation, which, in turn, activates HIF1α." (PMID 20663134, 2010). "We investigated in cell lines potential regulation of genes in the common metagene by hypoxia and by HIF1a, the main mediator of the hypoxia response in cancer." (PMID 20087356, 2010). "The hypoxia-inducible factors-1α and -2α (HIF-1α and HIF-2α) are transcription factors that are overexpressed in cancer and linked to cancer progression." (PMID 21073737, 2010). "We previously showed that cetuximab downregulates HIF-1α in cancer cells sensitive to anti-EGFR therapy through inhibition of HIF-1α protein synthesis, which was prevented by expression of a myristoylated Akt that is constitutively active." (PMID 21209911, 2010). "HIFα isoforms, particularly HIF-1α, have been shown to be key regulators of aerobic glycolysis in cancer cells." (PMID 20652061, 2010). "More importantly, 1, 9 PA can downregulate HIF-1α in cancer cells that are insensitive to cetuximab-induced inhibition of HIF-1α expression due to overexpression of oncogenic Ras (RasG12V)." (PMID 21209911, 2010). "Stabilisation and activation of HIF-1α transcription complex also correlates with tumour metastasis and poor prognosis in cancer patients." (PMID 20010940, 2010). "We demonstrated that the treatment of several human cancer cell lines with therapeutical doses of WR-1065 led to a strong induction of different VEGF-A mRNA isoforms independently of HIF-1α." (PMID 20334641, 2010). "Available data on the role of HIF-1α for the chemosensitivity of cancer cells under normoxic conditions are conflicting." (PMID 20706634, 2010). "In the study, for the first time, we found that TPZ acts in a novel manner to inhibit HIF-1α accumulation driven by hypoxia or growth factors in human cancer cells and in HepG2 cell-derived tumors in athymic nude mice." (PMID 21085474, 2010). "Expression of HIF-1α is characteristic of early stages of carcinogenesis and has been correlated with increased intratumoral angiogenesis, cancer progression, poor patient prognosis and chemo- as well as radio- resistance." (PMID 20569445, 2010). "We previously reported that cetuximab can markedly downregulate the high basal levels of hypoxia-inducible factor-1 alpha (HIF-1α) by inhibiting HIF-1α protein synthesis in cancer cell lines that are sensitive to EGFR inhibition." (PMID 21209911, 2010). "Here we used human ovarian SKOV-3 cancer cells as a model to probe the effect of triptolide on HIF-1α." (PMID 20932347, 2010). "A recent study demonstrated that culture in hypoxia and activation of HIF1α expands the sub-population of cells positive for cancer stem cell marker, CD133." (PMID 20104230, 2010).
cancer (continued). "New data on HIF-1 signaling and the potential for targeted therapies, including combinations of hormonal therapies for cancer and selective investigational HIF-1α inhibiting small molecules would be discussed." (PMID 21143841, 2010). "Cytoplasmic staining for HIF-1α was observed in many cancer cells, whereas nuclear staining was observed in only a part of them." (PMID 21118571, 2010). "Second, we found that 1, 9 PA sensitizes cancer cells to cetuximab treatment, and this effect of 1, 9 PA is dependent on the ability of 1, 9 PA to downregulate HIF-1α." (PMID 21209911, 2010). "Hypoxia-inducible factor-1α (HIF-1α) is a critical transcription factor responsible for adaptive responses of cancer cells to reduced O2 availability." (PMID 20932347, 2010). "A polymorphism in HIF-1α (P582S) has been found associated with increased HIF activity and poor prognosis in prostate cancer, but its significance with cancer risk is still incompletely understood." (PMID 20169098, 2010). "HIF-1α is a major stress regulator induced by cancer cells in response to ischaemia during tumour development." (PMID 20334641, 2010). "In cancer, genetic alterations in tumor suppressor genes and oncogenes also induce HIF-1α and HIF-2α overexpression, and lead to the transactivation of target genes." (PMID 21073737, 2010). "We present a novel mechanism whereby cancer cells with oncogenic KRAS mutation, and expressing both HIF-1α and HIF-2α, can maximize ATP production and minimize ROS generation." (PMID 21073737, 2010). "Hypoxia, primarily acting through HIF-1a, elicits a wide spectrum of changes in gene expression that contribute to the metastatic phenotype of cancer cells." (PMID 20102637, 2010). "Hypoxia is a common feature of human cancers, which induces a transcription programme mediated mainly by hypoxia-inducible factor-1α (HIF-1α) that promotes aggressive tumour phenotype." (PMID 20736942, 2010). "Based on this, targeting tumoral HIF-1α is under intense investigation as a therapeutic target for cancer chemotherapy." (PMID 20398289, 2010). "Previous studies have indicated that activation of HIF-1α has been identified in many solid tumors including carcinomas of the gastrointestinal tract." (PMID 20953377, 2010). "Here we demonstrate that in cancer cell lines c-Myc was degraded during hypoxia and specifically in A549 cells this degradation was dependent upon both HIF-1α and HIF-2α." (PMID 20046830, 2009). "Some authors report on protein expression of HIF-1α in the tissue of RCC to be significantly higher than in renal parenchyma adjacent to the cancer." (PMID 19302703, 2009). "Similar results have been shown for other cancer cells lines using an immunoblotting assessment of endogenous HIF-1α." (PMID 19347037, 2009). "HIF-1α is overexpressed in many human cancers compared to normal tissues due to the interaction of a multiplicity of factors and pathways that reflect specific genetic alterations and extracellular stimuli." (PMID 19347037, 2009). "In many solid tumors, intratumor hypoxia up-regulates HIF-1α expression, a response that is correlated with increased angiogenesis, oncogenesis, and poor cancer prognosis." (PMID 20003191, 2009). "HIF-1α expression is evaluated in many human cancers and HIF-1α levels of expression in cells correlate with tumorigenicity and angiogenesis." (PMID 20003271, 2009). "Several studies have confirmed that HIF-1α is a survival factor, as well as a key regulator of metastasis in various cancers." (PMID 19919690, 2009). "Our results on nuclear expression of HIF-1α were quite opposite to studies that describe nHIF-1α overexpression as a marker of unfavorable prognosis in human cancer." (PMID 19302703, 2009).